MIR1276 (microRNA 1276)
Synonyms: hsa-mir-1276; MIRN1276; mir-1276
Gene: MicroRNA gene on chromosome 15 (85,770,496 to 85,770,578, reverse strand). Ensembl gene ENSG00000221634.
Homologues: Orthologues: chimpanzee ptr-mir-1276 (100% identical).